RND2 (Rho family GTPase 2)
Description:
May be specifically involved in neuronal and hepatic functions. Is a C3 toxin-insensitive member of the Rho subfamily (By similarity).
Synonyms: ARHN; RHO7; RhoN
Tractability: Antibody: its Gene Ontology location is reachable by antibodies, with high confidence.
Gene: Protein-coding gene on chromosome 17 (43,025,222 to 43,032,041, forward strand). Ensembl gene ENSG00000108830.
Subcellular location: Cytoplasmic vesicle, secretory vesicle, acrosome membrane
Pathways (Reactome):
Signal Transduction: RND2 GTPase cycle
Gene Ontology:
Molecular function: protein binding; GTPase activity; protein kinase binding; G protein activity; GTP binding
Biological process: actin filament organization; regulation of actin cytoskeleton organization; signal transduction; small GTPase-mediated signal transduction
Cellular component: cytosol; plasma membrane; acrosomal membrane
Genetic constraint (gnomAD): Loss-of-function variants: 13 observed, 21.61 expected, observed/expected ratio (o/e) 0.6, 90% interval 0.39 to 0.96. The upper end of that interval is the gene's LOEUF score, 0.96, which puts it in group 4 of 6, group 1 being the genes least tolerant of losing a copy. Missense variants: 254 observed, 270.26 expected, observed/expected ratio (o/e) 0.94, 90% interval 0.85 to 1.04. Synonymous variants: 92 observed, 106.76 expected, observed/expected ratio (o/e) 0.86, 90% interval 0.73 to 1.02.
Homologues: Orthologues: chimpanzee RND2 (100% identical), macaque RND2 (99% identical), mouse Rnd2 (99% identical), rat Rnd2 (99% identical), dog RND2 (98% identical), rabbit RND2 (98% identical), pig RND2 (97% identical), guinea pig RND2 (94% identical), zebrafish rnd2 (70% identical). Paralogues in human: RND3 (63% identical), RND1 (52% identical), RHOA (38% identical), RHOC (37% identical), RAC1 (36% identical), RHOB (36% identical), RHOBTB2 (35% identical), RHOF (35% identical), RAC2 (34% identical), RHOBTB1 (34% identical), RHOD (34% identical), RHOG (34% identical), and 10 more.
Diseases named in the same sentence as RND2 in open-access papers:
RND2 is named in the same sentence as 16 diseases in open-access papers, as found by Europe PMC text mining. Sharing a sentence is not in itself a finding about the gene and the disease. The quoted sentences say what the papers report.
glioblastoma (4 papers, 2013 to 2025). The most malignant astrocytic tumor (WHO grade IV). "Collectively, all of these data suggested that apoptosis of glioblastoma cells was negatively regulated by RND2 expression." (PMID 32867814, 2020). "RND2 expression levels were significantly upregulated in human glioblastomas and suggest a poor prognosis in patients." (PMID 32867814, 2020). "The results showed that among 14 categories of human cancer, RND2 expression was evidently higher in glioblastomas." (PMID 32867814, 2020). "First, in the same location of human glioblastoma samples we found by immunochemistry staining that RND2 was negatively correlated with LC3B but positively correlated with p62, which are both markers of autophagy." (PMID 32867814, 2020). "Further, we detected the effect of RND2 in glioblastoma cells by up- or downregulating its expression in U87 and U251 cells." (PMID 32867814, 2020). "By summarizing data from the TCGA database, we found that expression of the small GTPase RND2 was significantly increased in human glioblastomas." (PMID 32867814, 2020). "It is known that p38 phosphorylation is an indicator of p38 MAPK signal activation; therefore, these results indicate that RND2 can reduce p38 MAPK signal activation in glioblastoma cells." (PMID 32867814, 2020). "Indeed, Rnd2 attenuates apoptosis and autophagy in glioblastoma cells by targeting the p38 MAPK signaling pathway." (PMID 34561615, 2021). "Because autophagy is one of the most important mechanisms of cell death, further, we wanted to explore whether RND2 played a key role in regulating autophagy in glioblastoma cells." (PMID 32867814, 2020). "Here, we have provided evidence showing that RND2 is an oncogene in human glioblastomas." (PMID 32867814, 2020). "Further, we measured the expression of RND2 in the three sub-classes of glioblastomas and found that, compared with the PN or CL GBM subtypes, RND2 expression was significantly lower in MES GBM." (PMID 32867814, 2020). "The forced expression of RND2 repressed p38 MAPK signalling, which inhibited glioblastoma cell autophagy and apoptosis in vitro and induced tumour growth in the xenografted mice in vivo." (PMID 32867814, 2020). "In summary, these data revealed that RND2 could be defined as a biomarker for glioblastomas and may indicate poor prognosis in GBM patients." (PMID 32867814, 2020). "Glioblastoma is characterized by high expression of RND2, which correlates with a negative prognosis." (PMID 41009560, 2025).
Anxiety (3 papers, 2021 to 2022). Intense feelings of nervousness, tension, or panic often arise in response to interpersonal stresses. "Rnd2-deficient mice also exhibited a significant increase in anxiety-like behavior when subject to a light/dark test." (PMID 34561615, 2021). "Thus, our results are in line with the view that adult neurogenesis is not a simple continuation of earlier processes from development, and establish a causal relationship between Rnd2 expression and anxiety." (PMID 34561615, 2021). "Consequently, anxiety-like behavior may be more sensitive to the loss of new neurons compared to memory processes, hence the behavior of Rnd2-deficient mice in the present study." (PMID 34561615, 2021). "We next examined the impact of Rnd2 suppression in adult-born DGNs on anxiety-like behavior by measuring avoidance responses to potentially threatening situations, such as open and bright environments." (PMID 34561615, 2021). "With this strategy, we demonstrate that Rnd2 is cell-autonomously required for the proper development of adult-born DGNs and critical for anxiety-like behavior." (PMID 34561615, 2021). "Finally, we assessed whether Rnd2 deletion in neonatally-born DGNs also affects anxiety-like behavior." (PMID 34561615, 2021). "Given our observation that Rnd2 is crucial for the survival of adult newborn neurons and their maturation within the DG, we studied whether the deletion of Rnd2 specifically in these cells impairs hippocampal-dependent memory, anxiety, and/or depression-like behaviors." (PMID 34561615, 2021). "Altogether, these experiments demonstrate that Rnd2 deletion in adult-born DGNs via a retroviral approach impacts anxiety-like behavior but does not affect memory and depression-like behavior." (PMID 34561615, 2021). "Interestingly, the suppression of Rnd2 in neonatally-born DGNs has no impact on anxiety-related behavior, suggesting that Rnd2 has specific and unique functions in DGNs generated during adulthood." (PMID 34561615, 2021). "In addition to cellular effects, we show that Rnd2 deletion in adult-born DGNs impacts anxiety-like behavior while depression-like behavior is not affected." (PMID 34561615, 2021). "In addition, suppression of Rnd2 in adult-born dentate granule neurons increases anxiety-like behavior whereas its deletion in pups has no such effect, a finding supporting the adult neurogenesis hypothesis of anxiety disorders." (PMID 34561615, 2021).
glioma (3 papers, 2013 to 2020). A benign or malignant brain and spinal cord tumor that arises from glial cells (astrocytes, oligodendrocytes, ependymal cells). "By contrast, the downregulation of RND2 enhanced p38 MAPK signalling activities and promoted glioma cell autophagy and apoptosis." (PMID 32867814, 2020). "Seven Rho GTPases (RND1, RND3, RAC3, RHOA, RAC2, RAC1 and RHOC) showed a significantly greater connectivity in grade IV glioma and seven (CHP, RHOD, RHOF, RHOB, RHOQ, RND2, RHOBTB3) showed greater connectivity in grade II glioma." (PMID 26132659, 2015). "Furthermore, we found that the level of RND2 mRNA was significantly increased in gliomas, regardless of whether they were low-grade or high-grade gliomas." (PMID 32867814, 2020).
melanoma (3 papers, 2009 to 2019). A malignant, usually aggressive tumor composed of atypical, neoplastic melanocytes. "Aza treatment sensitizes melanoma cells to therapeutics by upregulating RND2." (PMID 31024232, 2019).
medulloblastoma (1 paper, 2014). A malignant, invasive embryonal neoplasm arising from the cerebellum. "Semaphorin (co-expression network, p<1.23×10−5) and dopamine (intersect analysis, p<0.02) signaling pathways were exclusively enriched in Group 4 medulloblastoma and connected via co-expressed genes, DPYSL4, RND2 and SNCAIP that are all part of the same network cluster." (PMID 25412507, 2014).
neuroblastoma (1 paper, 2012). Neuroblastoma (NB) is the most common solid, extracranial childhood tumor. "For example RhoU, RhoBTB1 and especially Rnd2 are expressed in neuroblastoma, while Rnd3 is expressed in HeLa and neuroblastoma." (PMID 22916134, 2012).
Sepsis (1 paper, 2022). Sepsis is defined as life-threatening organ dysfunction caused by a dysregulated host response to infection. "Genes promoting sepsis progression including CLOCK, PPBP and Rho family GTPASE 2 (RND2) were upregulated in Native Hawaiian patients." (PMID 36450776, 2022).
Stroke (1 paper, 2012). Sudden impairment of blood flow to a part of the brain due to occlusion or rupture of an artery to the brain. "In stroke subjects, frontal, temporal and parietal lobe volumes were significantly smaller on the stroke side as compared to the non-stroke side, and to the RND1 and RND2 sides of non-stroke subjects." (PMID 23071639, 2012).
tumor (5 papers, 2020 to 2025). "The pancreatic polypeptide (Ppy) gene was the top significantly down-regulated gene in FMT-MI tumour tissues (log2(fold change) (log2FC) = −0.605, padj = 0.0144), followed by the Rho family GTPase 2 (Rnd2) gene (log2FC = −0.518, padj = 0.029)." (PMID 38400709, 2024). "As expected, the mice that were implanted with the RND2 overexpression U87 cells had larger tumours than the mice in the control group." (PMID 32867814, 2020). "To further evaluate the role of RND2 in clinical samples, we performed RT-PCR assays to examine the levels of RND2 expression in tumour tissues sampled from patients suffering from primary GBM." (PMID 32867814, 2020). "Most importantly, our study found that RND2 expression was inversely correlated with patient survival time and was positively correlated with tumour size." (PMID 32867814, 2020). "Furthermore, RND2 was negatively correlated with patient prognosis, while it was positively correlated with tumour size, suggesting that RND2 is a potential target for treating GBM." (PMID 32867814, 2020). "Additionally, the weights of the tumours in the RND2 overexpression group were significantly greater than those of the control group." (PMID 32867814, 2020). "Additionally, RND2 expression was positively correlated with tumour volume." (PMID 32867814, 2020). "Additionally, the mechanistic and direct role of RND2 in GBM tumour genesis is totally unexplored." (PMID 32867814, 2020).
cancer (1 paper, 2020). A tumor composed of atypical neoplastic, often pleomorphic cells that invade other tissues. "Besides, we found that RND2 decreased the phosphorylation of p38 by directly binding to p38 in the cytoplasm of cancer cells and we observed that RND2-mediated p38 MAPK signalling was critical for autophagy activities." (PMID 32867814, 2020). "In a summary, our data not only suggests RND2 as an alternative therapeutic target for malignant human cancers such as GBM but also provides a solid foundation for the development of a compound targeting RND2, which could be transformed into clinical applications and combined with chemotherapies." (PMID 32867814, 2020). "However, the activities of RND2 in cancer have not yet been demonstrated." (PMID 32867814, 2020).
RND2 also shares sentences with these, for which no sentence is quoted: breast carcinoma (2 papers); acute myeloid leukemia (1); anxiety disorder (1); brain tumor (1); depression (1); ovarian carcinoma (1).